FMR1 (fragile X messenger ribonucleoprotein 1)
Diseases named in the same sentence as FMR1 in open-access papers (continued):
Sharing a sentence is not in itself a finding about the gene and the disease.
fragile X syndrome (continued). "Fragile X syndrome (FXS) is the leading cause of inheritable intellectual disability in male children, and is predominantly caused by a single gene mutation resulting in expanded trinucleotide CGG-repeats within the 5’ untranslated region of the fragile X mental retardation (FMR1) gene." (PMID 24942544, 2014). "In humans, loss of FMR1, a protein with one RGG RNA-binding and two KH domains, causes the most common form of inherited mental retardation, the Fragile X syndrome (FXS)." (PMID 23874212, 2013). "The fragile X syndrome (FXS, MIM #300624), the most common cause of inherited mental retardation, is due to the amplification (> 200 repeats) of a sequence of CGG triplets in the 5' UTR of the FMR1 gene, followed by methylation of cytosines, including those of the promoter upstream." (PMID 22397687, 2012). "These ovarian genotypes and sub-genotypes have to be distinguished from classical FMR1 genotypes, which for decades have been used to, primarily, define neuro-psychiatric risks with premutation range (55–200 CGG repeats) and full mutation (fragile X syndrome) genotypes (>200 CGG repeats)." (PMID 22438971, 2012). "Metabotropic GluRs have been implicated in learning and memory processes, as well as a human intellectual disabilities (Fragile X syndrome), where the absence of a protein encoded by the Fragile X mental retardation 1 (FMR1) gene causes dysregulation of mGluR-dependent signalling." (PMID 23580048, 2011). "Fragile X syndrome (FXS; OMIM #300624), an X-linked neurodevelopmental disorder, is caused by the expansion of a CGG trinucleotide repeat in the 5’ untranslated region (UTR) of the Fragile X Messenger Ribonucleoprotein 1 (FMR1) gene." (PMID 40296143, 2025). "In the case of Fragile X syndrome, the expanded CGG repeats, found in the FMR1 gene, correlate with changes in chromatin structure, which include heightened DNA methylation and repressive histone modifications." (PMID 41035523, 2025). "From the total number of male patients, four patients (~1.8%) presented hypermethylation of the FMR1 gene promoter and abnormal number of CGG repeats, consistent with Fragile X syndrome." (PMID 40869951, 2025). "Fragile X Syndrome (FXS), the most common inherited cause of intellectual disability and autism spectrum disorder (ASD), results from disruption of the 5′ untranslated region of the FMR1 gene on the X chromosome." (PMID 41324081, 2025). "Fragile X Syndrome (FXS) is the most common form of inherited intellectual disability that is created by a trinucleotide repeat expansion (cytosine-guanine-guanine–CGG) at Xq27.3 on the upper end of the Fragile X Messenger Ribonucleoprotein gene (FMR-1)." (PMID 40003347, 2025). "Short Tandem Repeats (STRs, or microsatellites) are seen to influence the local DNAm state, with the classic pathological example of the hypermethylated expanded CGG trinucleotide repeat in the 5′UTR of FMR1 repressing transcription in Fragile X syndrome (FXS, MIM: 300624)." (PMID 38602535, 2024). "Fragile X syndrome (FXS) is an X-linked neurodevelopmental disorder caused by reduced or absent expression of the protein product (FMRP) of the fragile X messenger ribonucleoprotein 1 (FMR1) gene." (PMID 38540415, 2024). "Many individuals with fragile X syndrome show ASD-like social behavior impairments, some of which are recapitulated in Fmr1-KO mice." (PMID 39641273, 2024). "Here, we extend this work by testing predictions of the threshold metaplasticity hypothesis in a second mouse line with enhanced PF-Purkinje cell LTD, the Fmr1 knockout mouse model of Fragile X syndrome (FXS)." (PMID 37873217, 2024). "Fragile X syndrome (FXS) is caused by epigenetic silencing of the X-linked fragile X messenger ribonucleoprotein 1 (FMR1) gene located on chromosome Xq27.3, which leads to the loss of its protein product, fragile X messenger ribonucleoprotein (FMRP)." (PMID 38872088, 2024).
fragile X syndrome (continued). "Fragile X syndrome (FXS), the most common monogenic cause of inherited intellectual disability and autism spectrum disorder, is caused by a full mutation (>200 CGG repeats) in the Fragile X Messenger Ribonucleoprotein 1 (FMR1) gene." (PMID 38927312, 2024). "Fragile X syndrome (FXS), the most common genetic form of intellectual disability in males, is caused by silencing of the FMR1 gene associated with hypermethylation in the CGG expansion mutation in the 5′ UTR of FMR1." (PMID 37239005, 2023). "In fragile X syndrome, the STRs within the FMR1 gene are unstable and expand with DNA methylation so that CTCF cannot bind, resulting in silencing of the FMR1 gene." (PMID 39872109, 2023). "In-vivo PET studies also revealed reduced binding to the benzodiazepine binding site of the GABAA receptor in patients affected by fragile X syndrome in one portion of the PFC, exactly as observed in the Fmr1 KO mice at 12 weeks." (PMID 37547211, 2023). "In this way, we confirmed the interaction of FMR1, FXR1, and FXR2 of the Fragile X syndrome family as well as the E3 ubiquitin ligase MKRN2 with nsp3, both in context of single and nsp3/4 expression." (PMID 37905840, 2023). "Fragile X syndrome (FXS) is a neurodevelopmental disorder caused by a repeat expansion mutation in the promotor region of the FMR1 gene resulting in transcriptional silencing and loss of function of fragile X messenger ribonucleoprotein 1 protein (FMRP)." (PMID 36969493, 2023). "Individuals with Fragile X syndrome (FXS), the most common heritable form of intellectual disability, have a full-mutation sequence (>200 CGG repeats) which brings about transcriptional silencing of FMR1 and loss of FMR protein (FMRP)." (PMID 35626665, 2022). "Fragile X Syndrome (FXS) is caused by a trinucleotide expansion leading to silencing of the FMR1 gene and lack of expression of Fragile X Protein (FXP, formerly known as Fragile X Mental Retardation Protein, FMRP)." (PMID 35379866, 2022). "Hyper-expression of ADCY1 has been identified in a mouse model of Fragile X syndrome (FXS), which is predominantly caused by mutations in the FMR1 (Fragile X messenger ribonucleoprotein 1) gene and deficient expression of its gene product FMRP (FMR1 protein)." (PMID 36188604, 2022). "This establishes a correlation between hypoediting and FMR1 and FXR1 genes demonstrating a shared RNA editing patterns and molecular deficit between two closely related neurodevelopmental disorders, ASD and Fragile X syndrome." (PMID 38596700, 2022). "Many patients with fragile X syndrome (FXS) have sleep disturbances, and Fmr1 knockout (KO) mice (a model of FXS) have reduced sleep duration compared to wild type (WT)." (PMID 35720683, 2022). "In most fragile X syndrome patients, abnormal expansions of triplet repeat (CGG) in 5' untranslated region of the FMR1 gene induce hypermethylation, resulting in suppression of transcription." (PMID 34642413, 2021). "Currently, the laboratory diagnosis of fragile X syndrome is based on DNA analysis that determines the number of CGG repeats and/or the degree of methylation of FMR1." (PMID 34680911, 2021). "These initial studies demonstrated that FMR1 is also methylated and inactivated after the expansion of CGG repeats in fragile X syndrome." (PMID 34638292, 2021). "The 5′-untranslated region (5′ UTR) of the FMR1 gene has CGG tandem repeats, and when the repeats expand beyond 200, this leads to fragile X syndrome (FXS)." (PMID 33854084, 2021). "The protein product of CYFIP1 has been proved to interact with FMRP, the protein coded by the FMR1 gene, which is responsible for the Fragile X syndrome." (PMID 33019446, 2020). "While Fragile X syndrome itself is separate from autism, it is the leading monogenic cause of autism, as a significant proportion of individuals with FXS also meet the clinical diagnostic criteria for ASD and mutations in FMR1 are present in up to 5 percent of ASD cases." (PMID 33262688, 2020).
fragile X syndrome (continued). "Fragile X syndrome (FXS) is mostly due to the expansion and subsequent methylation of a polymorphic CGG repeat in the 5’ UTR of the FMR1 gene." (PMID 32111011, 2020). "A trinucleotide repeat expansion, greater than 200 CGG, with consequent methylation of the 5′UTR (untranslated region) of FMR1 gene, leads to Fragile X Syndrome (FXS), the most common form of intellectual disability and known monogenic cause of Autism Spectrum Disorder1." (PMID 32632326, 2020). "Furthermore, lncRNA FMR4 originating from Fragile X mental retardation 1 (FMR1) locus, which aberrant expansion causes autism, was able to improve hNPCs development, furthermore, dysregulation of FMR4 contributed to the pathophysiology Fragile X syndrome and/or Fragile X tremor/ataxia syndrome." (PMID 32514332, 2020). "Fragile X syndrome (FXS) is a rare genetic disorder caused by mutations on the FMR1 gene and the ensuing under-expression of its associated fragile X mental retardation protein (FMRP;)." (PMID 31519170, 2019). "Fragile X Syndrome (FXS) is a triplet repeat disorder, where runaway expansion of CGG repeats at the promoter region of FMR1 gene causes promoter hypermethylation leading to failure of gene transcription and subsequently loss of protein expression of Fragile X mental retardation protein (FMRP)." (PMID 30862080, 2019). "Although fragile X syndrome (FXS) is caused by a hypermethylated full mutation (FM) expansion with ≥200 cytosine-guanine-guanine (CGG) repeats, and a decrease in FMR1 mRNA and its protein (FMRP), incomplete silencing has been associated with more severe autism features in FXS males." (PMID 31405222, 2019). "Studies of young children with fragile X syndrome (FXS) and the FMR1 premutation have shown sensory challenges as early as infancy and into early childhood." (PMID 30233641, 2018). "In FMR1 knockout mice, injections of mGluR5 restore the AMPA receptors expression levels and prevent fragile X syndrome." (PMID 29934975, 2018). "Historically, investigations of FMR1 have focused almost exclusively on the clinical effects of CGG expansion within the categories of the premutation (55–200 CGG repeats) and fragile X syndrome (>200 CGG repeats)." (PMID 30197656, 2018). "In addition, deregulated MuSC activity in the absence of Fmr1 may have implications for fragile X syndrome, which is associated with muscle hypotonia during infancy." (PMID 28882193, 2017). "Fragile X syndrome (FXS) is a debilitating neurodevelopmental disorder that results from mutation of the FMR1 gene and loss of fragile X mental retardation protein (FMRP)." (PMID 28451631, 2017). "The fragile X mental retardation protein (FMRP), which when lost through epigenetic silencing of the FMR1 gene results in fragile X syndrome (FXS), is a prime candidate for mediating activity-dependent synaptic remodeling during critical periods." (PMID 29375303, 2017). "Fragile X Syndrome (FXS) is the most common monogenic cause of intellectual disability, where a “CGG” triplet expansion at the 5′-UTR of the FMR1 gene is responsible for the loss of the Fragile X mental retardation protein (FMRP), a synaptically expressed RNA-binding protein regulating translation." (PMID 27547454, 2016). "Fragile X syndrome (FXS) is the most common mental disorder caused by a CGG trinucleotide amplification on Xq27.3 in the 5′ untranslated region of fmr1 gene cloned and named in 1991, which suppresses production of fragile X mental retardation protein (FMRP)." (PMID 27239350, 2016). "Fragile X syndrome (FXS) is a form of inherited mental retardation that results from the absence of the fragile X mental retardation protein (FMRP), the product of the Fmr1 gene." (PMID 27517961, 2016).
fragile X syndrome (continued). "Here, we used an unbiased, genome-wide proteomic strategy to define the brain lipid raft proteome of Fmr1 knockout mice—an animal model of Fragile X syndrome—and test the hypothesis that raft association of subsets of proteins might be affected by homeostatic changes occurring in absence of FMRP." (PMID 25849048, 2015). "PI3K inhibitor LY294002 corrected dysregulated synaptic protein synthesis, excess AMPA receptor internalization and the increased spine density in Fmr1 knockout neurons, supporting PI3K as a potential therapeutic target for fragile X syndrome." (PMID 25767435, 2015). "LncRNA FMR4, that is located upstream and likely shares a bidirectional promoter with FMR1, becomes silenced too as a result of the CGG expansion in the 5′ UTR of FMR1 in fragile X syndrome." (PMID 24627686, 2014). "For example, FMR1, which is an RBP responsible for the fragile X syndrome, was found to bind specifically to the internal and bulge loops of RNA." (PMID 24447569, 2014). "Fragile X Syndrome (FXS), the most common form of inherited mental retardation, is caused by a trinucleotide repeat expansion (CGG) in the 5′-untranslated region of the fragile X mental retardation 1 (FMR1) gene located at Xq27.3." (PMID 25153074, 2014). "Fragile X Syndrome (FXS), the most common cause of familiar mental retardation, is associated in over 99% of cases to an expansion over 200 repeats of a CGG sequence in the 5’ UTR of the FMR1 gene (Xq27.3), leading to the hypermethylation of the promoter." (PMID 23914933, 2013). "In the case of fragile-X syndrome (FXS), disruption in the function of a single gene, FMR1, results in a variety of neurological consequences directly related to problems with the development, maintenance, and capacity of plastic neuronal networks." (PMID 22811939, 2012). "Fragile X syndrome (FXS) is the most common inherited form of intellectual disability, is frequently associated with co-morbid ASD, and is most commonly caused by transcriptional silencing of the FMR1 gene." (PMID 22900020, 2012). "Fragile X syndrome (FXS), the most common cause of inherited mental retardation, is caused by the expansion of CGG trinucleotide repeats in the 5′ UTR of the fragile X mental retardation 1 gene (FMR1)." (PMID 18213394, 2008). "Prosodic differences have also been observed in unaffected relatives of autistic individuals and in those with fragile X syndrome, although prosody has not been extensively studied among FMR1 premutation carriers." (PMID 40141125, 2025). "Fragile X Syndrome (FXS) is the most common cause of inherited intellectual disability, caused by CGG-repeat expansions (> 200) in the FMR1 gene leading to lack of expression." (PMID 38997701, 2024). "Fragile X syndrome (FXS) is a neurodevelopmental disorder caused by an expansion of the CGG trinucleotide repeats (more than 200, termed full mutation, FM) in the 5′ untranslated region of the Fragile X Messenger Ribonucleoprotein 1 (FMR1) gene on the Xq27.3 chromosome region." (PMID 39063191, 2024). "Substantial studies have demonstrated that the absence of FMR1 protein is closely related to fragile X syndrome, including mental retardation and abnormal behaviour." (PMID 37056926, 2023). "Fragile X syndrome (FXS) is the most frequent inherited form of intellectual disability (ID) and autism spectrum disorder (ASD), caused by the silencing of the FMR1 gene and, subsequently, the loss of its encoded protein, fragile X mental retardation 1 protein (FMRP)." (PMID 37759701, 2023). "Fragile X syndrome (FXS) is an X‐linked neurodevelopmental disorder that is caused by the functional loss of the fragile X messenger ribonucleoprotein 1 (Fmr1) gene, resulting in a reduction or absence of RNA‐binding protein fragile X messenger ribonucleoprotein (FMRP)." (PMID 37407501, 2023). "Absence of the fragile X messenger ribonucleoprotein 1 (FMRP) causes ASD and intellectual disability, commonly referred to as the fragile X syndrome." (PMID 36838876, 2023).
fragile X syndrome (continued). "Additionally, genetic causes, such as type 1A pseudohypoparathyroidism (GNAS1 gene), fragile X syndrome (FXS, FMR1 gene), or Turner syndrome, have been reported to be show association with POF." (PMID 37005611, 2023). "We show that a similar psychedelictryptamine, N,N-dipropyltryptamine(DPT), completely prevents audiogenic seizures (AGS) in an Fmr1 knockout mouse model of fragile X syndrome at a 10mg/kg dose but not at lower doses (3 or 5.6 mg/kg)." (PMID 37854624, 2023). "Fragile X syndrome (FXS) is a neurodevelopmental disorder that is often modeled in Fmr1 knockout mice where the RNA-binding protein FMRP is absent." (PMID 38048343, 2023). "There remains uncertainty whether knock-in mouse models can replicate the core etiology of fragile X syndrome (FXS) and methylate the Fmr1 gene." (PMID 35977823, 2022). "Fragile X Syndrome (FXS) is the leading single gene cause of inherited intellectual disability and autism spectrum disorder (ASD), and is caused by a cytosine-guanine-guanine (CGG) trinucleotide repeat expansion in the promoter region of the fragile X messenger ribonucleoprotein 1 (FMR1) gene." (PMID 36688132, 2022). "The FMR1 gene and the consequent lack of synthesis of FMR protein (FMRP) are associated with the fragile X syndrome, and FMRP plays a critical role in chromatin dynamics, RNA binding, mRNA transport, and mRNA translation." (PMID 36452120, 2022). "Fragile X syndrome (FXS) is an inherited disorder that is characterized by intellectual disability and is caused by the deficiency or absence of the Fmr1 gene, which encodes fragile X mental retardation protein (FMRP), an RNA binding protein in neurons that is essential for synaptic plasticity." (PMID 36429030, 2022). "Using our model, and data from multiple cohorts of animals, we conclude that Fmr1-knockout (KO) rats—rats missing the gene silenced in Fragile-X Syndrome (FXS)—do not differ from wild-type (WT) rats in PPI." (PMID 32144356, 2021). "Fragile X syndrome (FXS), an inherited developmental disorder characterized by mental retardation and symptoms of autism spectrum disorders (ASD), is caused by transcriptional silencing of the FMR1 gene, which encodes fragile X mental retardation protein (FMRP)." (PMID 33401721, 2021). "Most past research has focused on clinically-ascertained individuals with expansions in CGG repeats, either those with fragile X syndrome (> 200 CGG repeats), the FMR1 premutation (55–200 repeats), or in the gray zone (variously defined as 45–54 or 41–54 repeats)." (PMID 34456771, 2021). "The majority of Fragile X syndrome (FXS; OMIM 300624) cases are caused by a full trinucleotide (CGG) repeat expansion of more than 200 repeats in the 5′ untranslated region of FMR1 that results in hypermethylation of FMR1 and loss of expression of the RBP FMRP." (PMID 34564083, 2021). "Given the significant impact fragile X syndrome has on families, together with the lack of curative treatment, the FMR1 premutation is considered a prime candidate for population‐based screening programs (preconception/prenatal/newborn) internationally." (PMID 33184995, 2021). "Fragile X syndrome results from the absence of the FMR1 gene product—Fragile X Mental Retardation Protein (FMRP)." (PMID 34680911, 2021). "Individual (V:1) had a normal karyotype and a negative test for FMR1 repeat expansion (Fragile X syndrome; OMIM #300624)." (PMID 32715656, 2020). "Fragile X syndrome (FXS) is caused by a full mutation of the FMR1 gene (>200 CGG repeats and subsequent methylation), such that there is little or no FMR1 protein (FMRP) produced, leading to intellectual disability (ID)." (PMID 32576818, 2020). "FXTAS should be considered in the differential diagnosis of patients presenting with ataxia, even in the absence of tremor, and FMR1 DNA testing should be sought in those with a family history of fragile X syndrome or premutation disorders." (PMID 32466255, 2020).